LAIR1 (leukocyte associated immunoglobulin like receptor 1)
Diseases named in the same sentence as LAIR1 in open-access papers (continued):
Sharing a sentence is not in itself a finding about the gene and the disease.
tumor (continued). "Neither tumor (P = 0.56) nor stromal (P = 0.93) LAIR-1 expression in the whole discovery cohort significantly predicted OS." (PMID 36960400, 2023). "As such, our study confirms expression of LAIR-1 on tumor cells, similar to expression of PD-1, rather than PD-L1 on tumor cells." (PMID 36960400, 2023). "In addition, LAIR‐1 includes two ITIMs in its intracellular segment, and the ITIM receptors are an ideal target for tumor immunotherapy." (PMID 35702880, 2023). "Furthermore, using multiplexed QIF (mQIF), we investigated LAIR-1 protein expression across different subtypes of NSCLC and identified its localization in various tumor and stromal cell types comprising the NSCLC TME." (PMID 36960400, 2023). "Thus, besides formation of an ECM-rich and fibrotic tumor niche, TME-expressed collagens can function to promote immune evasion through their direct interaction with LAIR-1." (PMID 34121658, 2021). "To assess whether expression of these MMPs and collagen I in combination with LAIR-1 impacts survival, we performed bioinformatic analyses of tumor MMP1, MMP9, COL1A1 and LAIR1 mRNA expression using data from the TCGA database." (PMID 34691040, 2021). "The LAIR-1 with ITIM motifs have been shown to inhibit signalling from immunoreceptor tyrosine-based activation motif (ITAM) containing receptors; the role of these receptors in tumour development is well documented." (PMID 33396670, 2020). "In contrast, tumor-infiltrating T cells showed minimal or no expression of LAIR1." (PMID 40591413, 2025). "LAIR1 KO, antibody blockade, and an immunotherapy that incorporates a LAIR1-inhibitory module into a chimeric antigen receptor (CAR) all led to increased antitumor activity by CAR T cells, reduced M2-like TAMs, altered collagen networks, and increased survival rates in mouse tumor models." (PMID 40829176, 2025). "Indeed, it has been found by PCR that LAIR1 mRNA was upregulated in human RCC tumor tissues compared to the next non-tumor renal tissues." (PMID 40563506, 2025). "LAIR1 inhibition enhanced peripheral and intratumoral CD8 memory T cell populations, induced a phenotypic shift of M2-like macrophages toward M1 macrophages, and normalized tumor collagen IV and structural components in the TME, facilitating effective tumor–T cell interactions and tumor suppression." (PMID 40591413, 2025). "Interestingly, whereas combination therapy with NC410 and anti-PD-L1 increases tumour control, genetic deletion of LAIR-1 does not further increase the efficacy of anti-PD-L1 treatment." (PMID 38236251, 2024). "Since solely blocking LAIR-1 by NC410 in immunocompetent mice is not sufficient to induce tumour control, additional targeting of other pathways or immune checkpoints might be required." (PMID 38236251, 2024). "However, addition of NC410 to anti-PD-L1 treatment enhanced tumour control compared to isotype in Lair1+/+, but not in Lair1−/− mice (bottom-centre and bottom-right)." (PMID 38236251, 2024). "As collagen, along with other extracellular matrix components, plays a key role in tumour growth and progression, it is not surprising that LAIR-1, an inhibitory receptor that recognizes collagen, presents itself as a promising target for cancer immunotherapy in multiple recent studies." (PMID 38236251, 2024). "Again, we did not observe differences in tumour growth between Lair1+/+ and Lair1−/− mice." (PMID 38236251, 2024). "In addition, in the tumor microenvironment, we found that PPRC1 expression in LIHC and OV had the same trend as some immune-cell molecular markers such as CD200, CD200R1, and LAIR1, although, in SKCM we found that PPRC1 expression had the opposite trend to that of some immune cell molecular markers." (PMID 37109742, 2023). "LAIR‐1 may also participate a critical part in TIME of LGG by regulating the infiltration of immune cells, suggesting that LAIR‐1 might be used as a therapeutic target to regulate the anti‐tumor immune response." (PMID 35702880, 2023).
tumor (continued). "Similarly, neither stromal nor tumor LAIR-1 expression of patients with LUSC histologic subtype significantly predicted OS after surgery." (PMID 36960400, 2023). "LAIR-1 was multiplexed with lymphocyte markers (CD45RA, CD4, CD8, CD20, CD56), myeloid monocyte markers (CD14, CD68, CD163 for macrophages and CD66b for neutrophils), fibroblast marker (SMA), hematopoietic progenitor cells (HPC, CD34) and tumor marker (pan CK)." (PMID 36960400, 2023). "Thus, LAIR-1 primarily acts as an immunosuppressor rather than a tumor inhibitor." (PMID 36906534, 2023). "Interestingly, blockade of LAIR-1 plus anti–PD-L1 was unable to control the growth of MC38 tumors when treatment was initiated on day 9 after tumor implantation and also failed to promote infiltration or activation of lymphocyte populations under these conditions." (PMID 35230974, 2022). "LAIR1 is an immune inhibitory receptor, plays a negative role in solid tumor growth, and the activation of LAIR1 on immune cells may lead to suppression of anti-tumor immune responses." (PMID 34880206, 2021). "No direct evidence for the interaction of LAIR1 expressed by NK cells and collagen is reported so far; however, that indeed cross-linking of collagen can trigger an inhibiting signal in lymphocytes upon LAIR1 engagement has been demonstrated for T and B cells, APCs, and tumor cells." (PMID 24550913, 2014). "It has been described that anti-LAIR1 antibodies can react with epithelial ovarian carcinoma (EOC) specimens, but not with ovarian tissue near the tumor." (PMID 40563506, 2025). "We visualized the effect of anti-Lair1 antibody on interplay between CAR or non-antigen-specific (NAS) T cells, M2-like MΦ, and human GBM U87 tumor spheres." (PMID 40591413, 2025). "Together, our data suggest that mouse LAIR-1 interacts with collagen in a different manner than human LAIR-1 and that LAIR-1 blockade in immunocompetent mice does not impact tumour growth." (PMID 38236251, 2024). "Because LAIR-1 expression is believed to be restricted to hematopoietic-derived cells in healthy conditions, the identification of LAIR-1 on tumor cells of nonhematopoietic origin indicates a deregulation of LAIR-1 expression in the TIME." (PMID 36960400, 2023). "Furthermore, IF staining of human GBM tissues revealed that LAIR1+ cells were predominantly CD45+, with no significant overlap with EGFR-expressing tumor cells, a marker in most GBMs." (PMID 40591413, 2025). "Although NC410 is an effective LAIR-1 antagonist in vitro and is present to a high extent at the tumour site in vivo, it is not yet clear whether NC410 only functions by blocking LAIR-1:collagen interactions." (PMID 38236251, 2024). "Here we demonstrate that inhibition of TGF-β, PD-L1, and LAIR-1 was able to effectively control the growth of the collagen-rich murine MC38 colon and EMT6 breast carcinomas, resulting in tumor cures and long-term tumor-specific protection not achieved with individual compounds." (PMID 35230974, 2022).
cancer (64 papers, 2019 to 2026). A tumor composed of atypical neoplastic, often pleomorphic cells that invade other tissues. "In cancers, T cell number and activity are modulated via a direct binding of collagen to specific T cells receptors, including leukocyte-associated Ig-like receptor-1 (LAIR-1), discoidin domain receptor 1 (DDR1), and several integrins." (PMID 38969910, 2024). "Leukocyte-associated immunoglobulin-like receptor-1 (LAIR1), an immune receptor containing immunoreceptor tyrosine-based inhibiory motifs (ITIMs), has emerged as an attractive target for cancer therapy." (PMID 37845206, 2023). "Meta-analysis of human datasets showed an association between high collagen and LAIR-1 expression with low overall survival in glioblastoma multiforme and mesothelioma and other advanced cancer types." (PMID 36159809, 2022). "Beyond its implications in physiology, the activity of LAIR1 can be inappropriately involved in various autoimmune or inflammatory disorders and has been implicated in cancer physiopathology, including hematological neoplasms." (PMID 36555775, 2022). "In vivo, the deregulation of LAIR1 leads to an increase in uncontrolled inflammation, as well as its hyperregulation in some types of cancer, which has been associated with disease progression and may act as a predictor of clinical outcomes." (PMID 40563506, 2025). "Inhibition of LAIR1 signaling has been shown to render resistant cancer cells more susceptible to anti-PD-1/PD-L1 therapy, indicating that LAIR1 may serve as a potential biomarker for cancer immunotherapy." (PMID 37845206, 2023). "Leukocyte-associated immunoglobulin-like receptor-1 (LAIR-1) is an immune inhibitory receptor, high levels of LAIR-1 expression are associated with poor cancer differentiation and overexpression of LAIR-1 was significantly associated with worse overall survival in HCC." (PMID 37051536, 2023). "Its function in cancers is associated with the ability to activate transcription of genes that are responsible for cell proliferation (c-Myc and cyclins A and E), and to down-regulate immune response by reacting with leukocyte-associated immunoglobulin-like receptor 1 LAIR1." (PMID 37108193, 2023). "We have uncovered what we believe to be a previously unrecognized immunosuppressive LAIR1/factor XIII A/collagen IV pathway across various cancer types." (PMID 40591413, 2025). "For instance, LAIR1 was up-regulated in CSS-H tumors across 6 cancer types, and its expression was associated with the sensitization of 70 anti-cancer drugs." (PMID 39822281, 2025). "The evidence offers promising insights into the therapeutic potential of targeting LAIR1 in cancer treatment." (PMID 40591413, 2025). "Outperformance of anti–PD-1 antibody and 8R-70 CAR T cells by anti-LAIR1 antibodies is remarkable and further reinforces the potential of anti-LAIR1 therapeutic approaches in patients with cancer." (PMID 40829176, 2025). "Our study provides evidence that elucidates the previously uncharacterized LAIR1 signaling pathway in cancer immunosuppression and highlights the role of LAIR1 in enhancing antitumor effectiveness in models." (PMID 40591413, 2025). "Typically, LAIR1 is a surface molecule expressed by leukocytes, but there are some reports claiming it is expressed by cancer cells." (PMID 40563506, 2025). "As a result, there has been a growing interest over the past 5 years among scientists in investigating the role of LAIR1 in cancer progression and its potential as a target for therapeutic drug development." (PMID 40591413, 2025). "Given the role of LAIR1 as an immunosuppressive regulator across various cancers, it emerges as a promising focal point for targeted cancer therapy." (PMID 40591413, 2025). "Our findings have laid the groundwork for ongoing investigational new drug–enabling (IND- enabling) studies focused on developing a humanized LAIR1-blocking antibody or the 3-in-1 CAR T cells for cancer therapies." (PMID 40591413, 2025).
cancer (continued). "Focusing on the potential targeting of LAIR1 in cancer and therapeutic applications, two aspects should be considered." (PMID 40563506, 2025). "Multiple studies in mice implicate blockade of LAIR-1:collagen interaction in cancer as a promising therapeutic strategy." (PMID 38236251, 2024). "The increased expression of LAIR-1 in cancer cells elicits immune escape, reducing T cell activity and supporting an immune-excluded TME with the production of collagens." (PMID 38254772, 2024). "The widely expressed collagen-binding and immune-inhibitory receptor LAIR1 plays both cancer-promoting and cancer-inhibiting roles." (PMID 38831013, 2024). "This uniqueness is particularly relevant in light of recent findings showing that collagen promotes anti-PD-1/PD-L1 resistance in cancer through LAIR1-dependent CD8+ T cell exhaustion." (PMID 37925511, 2023). "Different LAIR1 expressions and predictive values have been found in several cancer types in recent years." (PMID 37845206, 2023). "Collagen-induced CD8+ T-cell exhaustion in cancer is mediated by the leukocyte-specific collagen receptor LAIR-1, which suppresses lymphocytic activity through SHP-1 signaling." (PMID 36960400, 2023). "In recent years, abnormal LAIR1 expression and various prognostic values have been documented in some cancer types, including leukemia, ovarian cancer, renal carcinoma, oral squamous cell carcinoma, and hepatocarcinoma." (PMID 37845206, 2023). "Expression of LAIR-1 on myeloid cells in cancer has been shown to play a role in immune suppression, also mediated primarily through collagen." (PMID 37662958, 2023). "We demonstrated that anti-LAIR1 antagonist antibodies have the potential to be applicable for anti-cancer therapeutic purposes." (PMID 36211388, 2022). "Blocking LAIR1 signaling in immune cells represents a promising strategy for development of anti-cancer immunotherapy." (PMID 36211388, 2022). "ITIM-containing immune inhibitory receptors including LAIR1 are becoming attractive immune checkpoint targets in cancer and immune-related diseases." (PMID 36211388, 2022). "Opposite effects of LAIR1 observed in vitro in several cancer cell lines (↑: increase; ↓: decrease)." (PMID 36555775, 2022). "Our result indicates that antagonizing LAIR1 signaling increases the cytotoxic activity of NK cells against cancer cells." (PMID 36211388, 2022). "These analyses highlighted the complexity of the TME and also supported targeting the collagen:LAIR-1 axis for cancer immunotherapy." (PMID 34121658, 2021). "Overall, we show that collagen fragments produced in cancer can mediate T cell suppression through LAIR-1, potentially contributing to systemic immune suppression." (PMID 34691040, 2021). "The effects and molecular mechanism of LAIR-1 in the progression of cancer needs further investigation." (PMID 32628130, 2020). "Six of these—CD5, CTLA4, TIGIT, LAIR1, PDCD1, and TNFRSF14—encode proteins that have been identified as immune checkpoints, defined broadly as receptors on immune cells that are exploited by cancer cells to escape the immune response." (PMID 39887658, 2025). "The potential of LAIR1 blockade in cancer immunotherapy is currently emerging." (PMID 38504978, 2024). "Also, DCIR blockade was recently shown to reduce the incidence of experimental inflammation-induced colon carcinoma and the potential of LAIR1 blockade in cancer immunotherapy is rapidly emerging." (PMID 38504978, 2024). "Furthermore, our researches have found two important intersection proteins, LCP2 and LAIR1, which possibly had potential prognostic value or serve as immunotherapeutic targets for cancers." (PMID 39367146, 2024). "LAIR1, an immune inhibitory receptor expressed on the majority of immune cell subsets, delivers an inhibitory signal after binding to collagen-like domains and confers poor prognosis in several cancer types." (PMID 37543576, 2023).
cancer (continued). "Altogether, our data suggest that the combination therapy of anti-PD-1/PD-L1 with anti-LAIR-1 or the anti-LAIR-1 monotherapy alone may be promising cancer immunotherapeutic strategies." (PMID 36960400, 2023). "We propose to block LAIR1 signaling as an anti-cancer immunotherapy." (PMID 36211388, 2022). "To test the hypothesis that LAIR1 blockade in immune cells induces anti-cancer immune responses, we generated a panel of anti-LAIR1 monoclonal antibodies from rabbits." (PMID 36211388, 2022). "The roles of LAIR1 in different types of cancer have been studied." (PMID 36211388, 2022). "In addition, a correlation analysis between NET score and 45 immune checkpoint genes (ICGs) revealed that CD48, CD86, and LAIR1 were the most significant NET-related checkpoint genes in all cancer types." (PMID 35432310, 2022). "The opposite effects of LAIR1 were observed in vitro depending on the cancer cell type." (PMID 36555775, 2022). "We hypothesized that in addition to ECM collagen, collagen fragments produced in cancer can mediate T cell immunosuppression through LAIR-1." (PMID 34691040, 2021). "Collectively, these results suggest tumoral mRNA expression of MMP1, MMP9, COL1A1 and LAIR1 significantly impacts survival of cancer patients, and therefore led to the hypothesis that MMP generated collagen I fragments might activate LAIR-1." (PMID 34691040, 2021). "Nonetheless, whether systemic immunosuppression in cancer is indeed mediated by collagen fragments via LAIR-1 should be further investigated." (PMID 34691040, 2021). "The role of LAIR-1 in cancer progression needs further investigation." (PMID 32628130, 2020). "The unique role of LAIR-1 and collagen in immune regulation is thought to influence multiple physiological processes including inflammation, wound healing, as well as progression of cancer and other disease states." (PMID 32719788, 2020). "Additional studies have indicated that collagen degradative products are suppressive to T cells and therefore blockade of LAIR-1 and potentially other collagen receptor interactions with collagen degradative products may further normalize immune function in cancer." (PMID 37662958, 2023). "However, it remains a question whether we can specifically and actively block LAIR1 signaling to activate immune responses for cancer treatment." (PMID 36211388, 2022). "However, it was unclear whether we could directly act on LAIR1 to block its signaling and stimulate anti-cancer immune responses." (PMID 36211388, 2022). "However, it was unclear whether we can specifically and actively antagonize LAIR1 signaling to achieve anti-cancer functions." (PMID 36211388, 2022). "Interestingly, TIM-3 was positively related to FTL and FTH1 in the most cancers, so does LAIR1." (PMID 33864445, 2021). "Furthermore, in multiple cancer types, CD93 expression positively correlates with the expression of various immune checkpoint molecules, including CD86, leukocyte-associated immunoglobulin-like receptor 1 (LAIR1), V-set immunoregulatory receptor (VSIR), and neuropilin 1 (NRP1)." (PMID 40943530, 2025). "Remarkably, five genes (PDCD1LG2, CD48, IDO1, LAIR1, and PDCD1) were found to be present in both the cancer-immunity cycle inhibitors and checkpoint genes categories." (PMID 38540734, 2024). "PILRΑ expression had a close and positive correlation with three ICGs including LAIR1, HAVCR2 and CD86 in almost all cancer types." (PMID 37652967, 2023). "LILRB4, LAIR-1 and OSCAR are all members of a larger Leukocyte Immunoglobulin-Like Receptor (LILR) family, several members of which have been described in cancer." (PMID 37662958, 2023). "Our result demonstrates that LAIR1 is functionally expressed on MDSCs and LAIR1 blockade inhibits MDSC activity and reactivates T cells in cancer patients." (PMID 36211388, 2022). "Data showed that the many immune checkpoints positively correlate with CD93 expression in many cancers, particularly NRP1, LAIR1, VSIR, and CD86." (PMID 36389798, 2022).